SAMD12 (sterile alpha motif domain containing 12)
Synonyms: FLJ39458; BAFME; BAFME1; FAME; FAME1; FCMTE1; MEBA
Tractability: No criterion of Open Targets' tractability assessment is met for any kind of drug.
Gene: Protein-coding gene on chromosome 8 (118,189,455 to 118,622,112, reverse strand). Ensembl gene ENSG00000177570.
Subcellular location (Human Protein Atlas): Cytosol; Golgi apparatus
Gene Ontology:
Molecular function: protein binding
Biological process: cell surface receptor protein tyrosine kinase signaling pathway
Cellular component: cytoplasmic side of plasma membrane
Genetic constraint (gnomAD): Loss-of-function variants: 9 observed, 14.58 expected, observed/expected ratio (o/e) 0.62, 90% interval 0.37 to 1.08. The upper end of that interval is the gene's LOEUF score, 1.08, which puts it in group 4 of 6, group 1 being the genes least tolerant of losing a copy. Missense variants: 229 observed, 244.74 expected, observed/expected ratio (o/e) 0.94, 90% interval 0.84 to 1.04. Synonymous variants: 86 observed, 93.94 expected, observed/expected ratio (o/e) 0.92, 90% interval 0.77 to 1.1.
Homologues: Orthologues: chimpanzee SAMD12 (99% identical), macaque SAMD12 (92% identical), dog SAMD12 (82% identical), rabbit SAMD12 (77% identical), pig SAMD12 (77% identical), mouse Samd12 (75% identical), guinea pig SAMD12 (74% identical), rat Samd12 (56% identical), tropical clawed frog samd12 (50% identical), zebrafish SAMD12 (31% identical), Drosophila melanogaster ave (18% identical), Caenorhabditis elegans ave-1 (13% identical). Paralogues in human: SAMD10 (35% identical).
Diseases named in the same sentence as SAMD12 in open-access papers:
SAMD12 is named in the same sentence as 41 diseases in open-access papers, as found by Europe PMC text mining. Sharing a sentence is not in itself a finding about the gene and the disease. The quoted sentences say what the papers report.
benign adult familial myoclonic epilepsy (3 papers, 2020 to 2023). "One is the benign adult familial myoclonic epilepsy (BAFME), caused by the abnormal expansion of (TTTCA)n and (TTTTA)n in intron 4 of sterile α-motif domain-containing 12 (SAMD12), in which SAMD12 protein is significantly lowered in patients’ brain (occipital lobe)." (PMID 35084690, 2023).
epilepsy (3 papers, 2019 to 2023). A brain disorder characterized by episodes of abnormally increased neuronal discharge resulting in transient episodes of sensory or motor neurological dysfunction, or psychic dysfunction. "This is true for repeats located outside of the region targeted by the panel, such as in familial adult myoclonic epilepsy 1 (FAME1) where intronic repeat expansion variants in SAMD12 are associated with epilepsy." (PMID 37834053, 2023). "Familial cortical myoclonic tremor with epilepsy (FAME) is a slowly progressing cortical tremor mapping to various genomic loci, including intronic expansions in SAMD12 for FAME1." (PMID 31664039, 2019).
breast carcinoma (2 papers, 2013 to 2018). "PREX1, CPNE1, and SAMD12 have, respectively, fused with other genes in breast cancer cell-lines: NFS1-PREX1 in SK-BR-3, CPNE1-PI3 in BT-474, and PHF20L1-SAMD12 in HCC1954." (PMID 23972288, 2013).
Liver fibrosis (2 papers, 2023). "Liver fibrosis-derived exosomal miR-106a-5p facilitates the malignancy by targeting SAMD12 and CADM2 in hepatocellular carcinoma." (PMID 38098508, 2023). "Exosome-derived miRNA of liver fibrosis modulated tumorigenesis by targeting SAMD12 and CADM2 in HCC." (PMID 37228062, 2023). "Subsequently, we investigated whether miR-106a-5p could facilitate the process of liver fibrosis to HCC by modulating the expression of SAMD12 and CADM2." (PMID 37228062, 2023).
arterial hypertension (1 paper, 2020). "For cardiac traits, the top interaction involved SNPs rs1383819 in SNTG1 and rs1493939 (138kb from 5’ of SAMD12) with Bonferroni-adjusted LRT p: 0.0228 which was significantly associated with history of arterial hypertension." (PMID 32915819, 2020).
glaucoma (1 paper, 2023). Increased pressure in the eyeball due to obstruction of the outflow of aqueous humor. "Database analysis revealed that seven host genes (NEAT1, SAMD12, KDM5D, ZFY, EIF1AY, TXLNGY, and DDX3Y) of nine DEcircRNAs were also differentially expressed in blood samples of patients with glaucoma, and the trend of differential expression of circRNAs and host genes was consistent." (PMID 37805546, 2023).
Langer-Giedion syndrome (1 paper, 2008). "Six probes were screened in the 8q24 region associated with Langer-Giedion syndrome, in TRPS1 (2 probes), EIF3S3 (1 probe), EXT1 (2 probes) and SAMD12 (1 probe)." (PMID 18925931, 2008).
liver cancer (1 paper, 2023). An epithelial or non-epithelial malignant neoplasm that arises from the liver. "SAMD12 and CADM2 were diminished in liver cancer cell lines, and their knockdown of them exacerbated the proliferation capacities of liver cells in vitro." (PMID 37228062, 2023).
osteosarcoma (1 paper, 2023). A usually aggressive malignant bone-forming mesenchymal neoplasm, predominantly affecting adolescents and young adults. "To assess the function of CNK2 and its binding partner SAMD12 in an in vivo context, we used CRISPR-Cas9 to knockout their respective genes in osteosarcoma cells and generated two clonal cell lines for each KO." (PMID 37322019, 2023).
type 2 diabetes (1 paper, 2018). "A family-based study of 859 Mexican Americans showed that the degree of methylation at top regions including TXNIP, ABCG1 and SAMD12 genes and two intragenic regions accounted for 7.8% of the heritability of type 2 diabetes in Mexican Americans." (PMID 29164275, 2018).
cancer (5 papers, 2017 to 2024). A tumor composed of atypical neoplastic, often pleomorphic cells that invade other tissues. "Overall, these data indicate that CNK2 and SAMD12 are required for metastasis in an in vivo cancer model." (PMID 37322019, 2023). "In summary, our work identifies the scaffold protein CNK2A and its binding partner SAMD12 as crucial regulators of cancer cell motility and invasion." (PMID 37322019, 2023). "Interestingly, human CNK2 and the HYP homolog SAMD12 have recently been shown to control cancer cell migration by mediating ARF6 activation induced by AXL signaling." (PMID 38388830, 2024). "Together, this work identifies CNK2 and its partner SAMD12 as key components of a novel pro-motility pathway in cancer cells, which could be targeted in metastasis." (PMID 37322019, 2023). "We discovered that, like CNK2 knockdown, depletion of SAMD12 impaired cell migration and 2D invasion in multiple cancer cell lines, and 3D invasion in HOS cells, establishing SAMD12 as a positive regulator of cell motility." (PMID 37322019, 2023). "However, the most targeted gene in both cell lines, SAMD12, was not identified in cancer previously." (PMID 28981542, 2017).
tumor (4 papers, 2019 to 2025). "KO of CNKSR2 or SAMD12 did not affect the size of liver tumours and liver weight, suggesting that reduced tumour burden caused by loss of CNK2 or SAMD12 is due to impaired cell invasion and not tumour growth after colonization." (PMID 37322019, 2023). "Our results uncovered that down-regulated SAMD12 and CADM2 exacerbated the proliferation potency, demonstrating the tumor suppression potential of SAMD12 and CADM2 in liver tumors." (PMID 37228062, 2023). "Mice injected with control cells displayed a strong bioluminescent signal in the abdominal region after 3 weeks, indicative of metastatic tumour formation, that was drastically reduced by both CNKSR2 KO or SAMD12 KO." (PMID 37322019, 2023). "Regarding tumor stages, SAMD12+ cells were predominantly expressed in stage II tumors, VIM in stage Ib, and both MKI67 and RPLP1 exhibited higher expression levels in stage IV, indicating their roles in advanced tumor progression." (PMID 40666516, 2025). "SAMD12 and CADM2 may play an alternate role in postoperative effects and tumor size, possibly contributing to carcinogenesis." (PMID 37228062, 2023).
SAMD12 also shares sentences with these, for which no sentence is quoted: adult familial myoclonic epilepsies (2 papers); Alzheimer disease (1); amyotrophic lateral sclerosis (1); autoimmune disease (1); Crohn disease (1); developmental delay (1); diabetes (1); epilepsy syndrome (1); fibrosis (1); Friedreich ataxia (1); Fuchs endothelial corneal dystrophy (1); genetic disorder (1); head and neck tumors (1); hepatocellular carcinoma (1); Huntington disease (1); inflammatory bowel disease (1); Intellectual disability (1); language delay (1); Motor delay (1); myoclonic epilepsy (1); myotonic dystrophy type 2 (1); neurodevelopmental disorder (1); neuronal intranuclear inclusion disease (1); schizophrenia (1); Seizure (1); spinocerebellar ataxia type 31 (1); spinocerebellar ataxia type 37 (1); spinocerebellar ataxia type 8 (1); temporal lobe epilepsy (1).